VSNL1 (visinin like 1)
Diseases named in the same sentence as VSNL1 in open-access papers (continued):
Sharing a sentence is not in itself a finding about the gene and the disease.
tumor (24 papers, 2008 to 2025). "Deficiency or reduced expression of VSNL1 by knockdown in vitro has been reported to increase the motility of cancer cells, suggesting a potential tumor suppressor function of the protein." (PMID 35595817, 2022). "The intense tumor expression of VSNL1, one of the ZG markers, also supports a ZG identity of the tumor." (PMID 38505749, 2024). "This lack of expression is unlikely to be due to the differences between scRNA-seq and snRNA-seq because the one MBEN tumor in our cohort with scRNA-seq data clearly shows a group of GABRD + /VSNL1+ cells." (PMID 38191555, 2024). "Based on our snRNA-seq data, VSNL1 is only expressed in tumor cells mimicking migrating and postmigratory GNs." (PMID 38191555, 2024). "Hub gene Camk2d was the most significantly changed gene within a downregulated module (i.e., muscle contraction) and Vsnl1 gene, related to cell cycle checkpoints, is highly expressed in the invasive tumor group." (PMID 35158756, 2022). "VSNL1 is an important modulator of tumor biology that regulates the expression of adenylyl cyclase in a cAMP-dependent manner." (PMID 33376484, 2020). "VSNL1 expression was significantly correlated with age, tumor size, depth of invasion, Lauren's classification, lymph node and distant metastases, regional lymph node stage, and TNM stage (all p < 0.05)." (PMID 33376484, 2020). "VSNL1 is a member of the neuronal EF-hand calcium sensor protein family and plays a role in regulating tumor cell invasion and migration." (PMID 33376484, 2020). "In c-Myc transgenic lung tumors expression of the tumor suppressor Vsnl1, i.e. a member of the neuronal Ca2+ sensor protein family was highly repressed." (PMID 29254206, 2017). "Among the top 15 predicted targets (ordered by increasing mirSVR score), VSNL1 is a known tumor-suppressor gene regulating cell migration in several cancer types." (PMID 26683098, 2016). "VSNL1, a marker for the normal zona glomerulosa (ZG), was also abundant in the tumor." (PMID 38505749, 2024). "Furthermore, we identified eight hub genes (VSNL1, TH, PCP4, IGDCC3, RAD51AP2, MUC2, BUB1, and BUB1B) that promoted tumor progression and were associated with prognosis according to the Kaplan–Meier and ROC curve analyses." (PMID 36979826, 2023). "On the other hand, VSNL1 is known to inhibit cell migration and behaves as tumour suppressor in several cancer types: its downregulation may lead to increased migration rate in GBM cells." (PMID 26683098, 2016). "Within each tumor, we observed that taurine intensities were significantly higher in the more differentiated MAP2 + /VSNL1+ regions compared to the MAP2 + /VSNL1- areas (t-test p value < 0.01)." (PMID 38191555, 2024). "The precise functions of VSNL-1 have not been elucidated, but it appears to have several roles in tumour invasion and metastasis." (PMID 38909013, 2024). "By using microarray technology it was reported that in MIF-reduced NB cells there was a downregulation of certain genes associated with tumor development including IL-8 and C-met along with upregulation of the tumor-suppressor genes EPHB6, visinin-like protein 1 (VSNL-1), and BLU." (PMID 32155795, 2020). "VSNL1 expression was not significantly correlated with sex, tumor location, differentiation, or histological classification (p > 0.05)." (PMID 33376484, 2020). "MiR-21, which is upregulated in many tumours, was predicted to target PITX2 and VSNL1 in our study." (PMID 27013928, 2016). "Visinin-like protein 1 (VILIP-1, gene name VSNL1), a member of the family of neuronal calcium sensor proteins, modulates the levels of cyclic nucleotides, induces cell differentiation, and has recently been identified as a putative tumor migration suppressor gene." (PMID 22479362, 2012).
cancer (13 papers, 2008 to 2023). A tumor composed of atypical neoplastic, often pleomorphic cells that invade other tissues. "Although VSNL1 is involved in tumorigenesis in various types of cancer, the significance of myristoylation, Ca2+‐binding, or dimerization has not been investigated." (PMID 37096864, 2023). "The role of VSNL1 in tumorigenesis is reportedly cancer type dependent." (PMID 37096864, 2023). "Other identified common up-regulated hub genes such as AKAP12, WFDC2, CALD1, and VSNL1 are related to drug resistance in various cancers although their involvement in oxaliplatin resistance in CRC was not identified and can be reported as protentional biomarkers which merits further exploration." (PMID 37535601, 2023). "VSNL1 was primarily localized in the cytoplasm and nuclei of cancer cells." (PMID 33376484, 2020). "VSNL1 regulates SNAIL1, which is a transcription factor with cAMP-dependent function, and SNAIL1 expression prevents epithelial-mesenchymal transition in cancer cells." (PMID 35595817, 2022). "VSNL1 downregulation was common to all GBM cell lines and, on average, more pronounced with respect to other cancer cell lines, with the only exception of SN-K-BE." (PMID 26683098, 2016). "This protein, VILIP-1 (gene name VSNL1), was established to be a member of the visinin-recoverin or neuronal calcium sensor (NCS) protein family and has been identified as having a role in human neurological disease and cancer." (PMID 20419170, 2010).
neurodegenerative disease (5 papers, 2015 to 2025). A disorder of the central nervous system characterized by gradual and progressive loss of neural tissue and neurologic function. "Because one important mechanism by which genetic variants may affect risk for neurodegenerative disease is to alter the transcription of their gene products in brain, we evaluated whether VSNL1 expression in frontal cortex is associated within or nearby the VSNL1 locus." (PMID 25806004, 2015).
infection (3 papers, 2020 to 2025). The state of being infected such as from the introduction of a foreign agent such as serum, vaccine, antigenic substance or organism. "Substantially decreased P2X3/P2Y2 expression was found in BGC-823 and SGC-7901 cells 72 h after infection with VSNL1 shRNA2." (PMID 33376484, 2020). "Our study found that after 72 h infection with VSNL1 shRNA2, the expression of P2X3 and P2Y2 decreased substantially." (PMID 33376484, 2020).
colorectal (1 paper, 2023). "Because dysregulation of the Wnt/β‐catenin signaling pathway by APC inactivation is the first step in a multistep genetic model for most CRCs,42 VSNL1 may be involved in the initiation of colorectal carcinogenesis." (PMID 37096864, 2023).
VSNL1 also shares sentences with these, for which no sentence is quoted: Cognitive impairment (10 papers); dementia (5); non-small cell lung carcinoma (5); epilepsy (3); esophageal SCC (3); frontotemporal dementia (3); hippocampal atrophy (3); neurological disease (3); skin cancer (3); Acute encephalopathy (2); adenocarcinoma (2); amyloid (2); Atrophy (2); behavioral variant frontotemporal dementia (2); Brain atrophy (2); dementia with Lewy bodies (2); leukemia (2); adrenal tumor (1); adrenocortical adenoma (1); Anxiety (1); brain disorder (1); breast carcinoma (1); cerebral (1); Cerebral atrophy (1); Cerebral ischemia (1); cholangiocarcinoma (1); cryptococcosis (1); delirium (1); diabetes mellitus (1); encephalitis (1).
A further 17 diseases each share a sentence with VSNL1 in 1 paper.